CTCF (CCCTC-binding factor)
Diseases named in the same sentence as CTCF in open-access papers (continued):
Sharing a sentence is not in itself a finding about the gene and the disease.
tumor (continued). "Notably, sh-CTCF significantly increased the proportion of NK cells and exhibited a pronounced inhibitory effect on tumor growth." (PMID 39623397, 2024). "Interestingly, knockdown of CTCF partially reversed the promotion of tumour growth by RPL35A overexpression (p < 0.01)." (PMID 38436544, 2024). "Furthermore, it has also been reported that TGF-β/β2SP/CTCF is involved in regulating tumor suppression in human stem cell disorder BWS19." (PMID 37414929, 2023). "Moreover, very recently, a study highlighted a novel TGF-β and H19 (known to bind CTCF) signaling axis in tumor-initiating hepatocytes that importantly regulates hepatic carcinogenesis." (PMID 37414929, 2023). "Finally, CCCTC-binding factor (CTCF) is a tumor suppressor and involved in many cellular processes, with approximately 11.3–20.4% of ML-DS cases harboring CTCF gene mutations." (PMID 36035173, 2022). "Together, these data strongly argue for a tumour suppressive role of CTCF." (PMID 35993175, 2022). "Furthermore, the promoting function of exosomal CTCF-mediated IGF2-AS through the miR-579-3p/MSH6 axis in OS cell resistance to CDDP was confirmed in tumor-bearing nude mice." (PMID 35693981, 2022). "The CTCF downregulates, or inhibition also governs the FoxO signal pathway and delays tumor growth." (PMID 36251702, 2022). "Moreover, recent studies are showing that two main regulators of genome topology (i.e., CTCF and COHESIN) bind chromatin in a sex-specific manner and that mutations at CTCF binding sites can act as tumor drivers." (PMID 36273184, 2022). "Alteration of either CTCF or histone gene cluster 1 was common, occurring in 17% of tumours." (PMID 34753926, 2021). "Finally, the aberrant transcriptional silencing of tumor suppressor genes is accompanied by dynamic changes in chromatin structure mediated by CTCF." (PMID 35011637, 2021). "Additionally we found the transcriptional profile of histone gene cluster 1 and CTCF altered tumours shared hallmarks of hyperdiploid ALL suggesting a ‘hyperdiploid like’ subtype." (PMID 34753926, 2021). "In a word, our findings showed that circESRP1 and CTCF gene could be designated in suppressive tumor metastasis and progression in RCC, and these might be novel strategies for the treatment of malignant ccRCC." (PMID 34775467, 2021). "In addition, inactivation or deletion of CCCTC-binding factor (CTCF) and zinc finger homeobox 3 gene (ZFHX3), encoded by tumor suppressor genes on chromosome 16q22 can also affect the occurrence of EC." (PMID 32412912, 2020). "Furthermore, rescue assays, including in vivo tumor growth assays and apoptosis assays, demonstrated that CTCF sustains CRC proliferation and chemotherapy resistance by activating the Hedgehog signaling pathway." (PMID 32688344, 2020). "Previous data have demonstrated a role for functional CTCF as a tumor suppressor." (PMID 32503656, 2020). "The flow cytometry detected the effect of CTCF on tumour growth in nude mice." (PMID 30873749, 2019). "That SMARCB1 KD leads to elevated accessibility at CTCF binding sites is particularly noteworthy given recent findings that a SMARCB1-excluding non-canonical SWI/SNF complex (ncBAF, also termed GBAF) preferentially targets CTCF sites in mESCs and several tumor cell lines." (PMID 31033435, 2019). "Lastly, the effect of CTCF on tumour growth was determined in nude mice." (PMID 30873749, 2019). "Inhibition of CTCF regulated the FoxO signalling pathway, which retarded tumour growth in vivo." (PMID 30873749, 2019). "Tumours in Ctcf+/− mice compared to WT mice also exhibit increased aggressiveness in terms of invasion, metastatic dissemination and mixed epithelial/mesenchymal differentiation, confirming CTCF as a haploinsufficient tumour suppressor." (PMID 30513694, 2018). "Moreover, the bowel weight (P=0.0028) and number of tumor nodules in the bowels (P<0.001) were also significantly reduced in the CTCF-knockdown A2780 group." (PMID 28977939, 2017).
tumor (continued). "CTCF knockdown significantly inhibited cell migration, invasion and tumor metastasis." (PMID 28977939, 2017). "Although they found that CCCTC-binding factor (CTCF) is likely to play a pioneering role in translating natural genetic variation in chromosomal architecture, we still strive to understand tumor-specific epigenetic features that render possible progression toward such disease." (PMID 28359301, 2017). "The mechanism by which LOH 16q increases the recurrence risk in WT may involve the effects of LOH 16q on certain tumor-associated genes such as E2F4, COX4, and CTCF." (PMID 29029528, 2017). "CTCF by itself does not modify epigenetic marks, but it interacts with epigenetic writers to alter the expression of oncogene and tumour suppressor genes through variants of this mechanism." (PMID 28587163, 2017). "To further examine whether CTCF silencing affects tumor growth in vivo, we subcutaneously injected 1×107 vector- or shCTCF1-transfected SKOV3 cells into nude mice." (PMID 28977939, 2017). "It was also postulated that CTCF itself acts as a tumor suppressor." (PMID 26833217, 2016). "It has also been postulated, that CTCF itself acts as a tumor suppressor." (PMID 26833217, 2016). "Disruption of molecular boundaries mediated by CTCF may facilitate the epigenetic silencing of tumor suppressor genes." (PMID 25352953, 2014). "CTCFL, the paralogous factor of CTCF, is expressed in germ cells and in some tumour types." (PMID 25294833, 2014). "It is unclear whether aberrant expression of BORIS interferes in tumour cells with the normal function of CTCF, or it elicits CTCF independent functions." (PMID 22724006, 2012). "Consequently, CTCF can now be seen as one of the epigenetic components that allows the proper configuration of tumor suppressor gene promoters." (PMID 21663659, 2011). "Furthermore, in tumour cell lines where CTCF silences genes by DNA methylation, conditional expression of BORIS leads to replacement of CTCF by BORIS at these genes, resulting in local demethylation and gene activation." (PMID 21811597, 2011). "To confirm the contribution of CTCF to the protection of tumor suppressor gene promoters against epigenetic silencing, we decided to generate a large set of independent stably integrated constructs carrying the Rb promoter fused to the GFP reporter gene, where the promoter had a mutated CTCF site." (PMID 21663659, 2011). "The regular loss of 16q in these and other breast tumours implies the presence of relevant tumour-suppressor gene(s) on 16q; although various tumour-suppressor genes have been implicated, for example CTCF, none have been proven as pathogenic." (PMID 15700031, 2005). "Apart from a few zinc-finger proteins, such as WT1, BCL11A, Evi9, EWS, TLS, GLI, and CTCF, the function of the majority of zinc-finger proteins in tumour occurrence and development is unknown." (PMID 15354214, 2004). "In vivo experiments corroborated that CTCF knockdown could reduce tumor growth." (PMID 39623397, 2024). "Genomic profiling revealed no actionable targets but NOTCH1 and KDM6A frameshift and CTCF splice site mutations (no MYB/L fusion) with a low tumor mutational burden (TMB), microsatellite stable (MSS) and negative programmed death ligand 1 (PD-L1) were observed." (PMID 39451738, 2024). "Considering the tumor suppressing function of FOXO3, rs17069665 and rs4946936 might influence RMS risk and prognosis via regulating the expression of FOXO3 by altering the bindings to MYC, CTCF and/or RELA." (PMID 38720807, 2024). "An interaction of cohesin proteins with NPM1 could be mediated by CCCTC-binding factor—a transcription factor that regulates tumor suppressor loci—which has been shown to bind and interact with both, potentially contributing to their role in stem cell self-renewal." (PMID 36693840, 2023).
tumor (continued). "These have been observed to displace CTCF from their binding sites, proteins that enforce “gene neighborhoods” and regulate gene expression by ensuring distal enhancers are insulated to only activate genes within their neighborhood, a guardian role known to be tumor suppressive." (PMID 37884500, 2023). "Despite these simplistic assumptions that could indeed average different situations in vivo, our model was successful in predicting the general trend and the order of magnitude by which different CTCF levels affect the clonogenic survival curves in the two tumor cell lines under study." (PMID 35409255, 2022). "However, the decrease in survival in stem cells was lower than in the tumor cells that retained a higher CTCF level, which may indeed be due to the faster recovery of CTCF levels in the first hour upon auxin wash off." (PMID 35409255, 2022). "As CTCF was initially identified as a transcriptional repressor of the c-Myc gene, we speculated that interaction of CTCF with circESRP1/miR-3942 might modulate c-Myc expression and further affected the tumor phenotypes of RCC." (PMID 34775467, 2021). "Furthermore, inhibition of CTCF could promote the FoxO signalling pathway and retard tumour growth in vivo." (PMID 30873749, 2019). "Thus, against previous hypothesis that considers an oncogenic property for BORIS, these data indicate that BORIS and CTCF might act as a tumor suppressor." (PMID 30323717, 2018). "Sufficient evidence proves that CTCF could be a tumor suppressor gene." (PMID 24393203, 2014). "We also analyzed the co-expression of CTCF and IL6 in different tumor regions using data from Xiao-Jun Ma and collaborators." (PMID 40143084, 2025). "Compared with the control group, tumour size of RPL35A overexpression group was the largest (p < 0.05), while CTCF knockdown group was the smallest (p < 0.01)." (PMID 38436544, 2024). "Furthermore, knocking down CTCF could inhibit tumor growth in vivo." (PMID 39623397, 2024). "Two GRNs, albeit comprising a smaller number of tumor cells, showed high activity for the TCF7L2 regulon (along with KLF8, FOXK1, FOXP2, and BACH1) (labeled TCF7L2+) and CTCF (along with MAFG and NR1H) (labeled CTCF+), respectively." (PMID 38968122, 2024). "Transcriptional factor (TF) analysis highlighted the relative activation of EZH2 and CTCF in GSCL cells, and their activation was found to be correlated with tumor cell stemness, proliferation, and drug resistance." (PMID 37964983, 2023). "Our previous data demonstrated that CTCF and PACERR bind to the promoter region of PTGS2, and both of them are indispensable for the M2 polarization and pro‐tumour functions of TAMs." (PMID 35184402, 2022). "As U2OS cells exhibit approximately twice the amount of CTCF compared to HeLa Kyoto cells, residual CTCF levels after depletion in U2OS were still higher, leading to a lower impact on survival relative to the other tumor type." (PMID 35409255, 2022). "Therefore, we speculated that exosomes from tumor cells delivered CTCF to activate IGF2-AS." (PMID 35693981, 2022). "Based on these findings, we proposed that circESRP1/miR-3942/CTCF positive feedback loop negatively affected the c-Myc-EMT signaling pathway in ccRCC tissues, thereby impacting the tumor behaviors of RCC." (PMID 34775467, 2021). "We validated that the overexpression of circESRP1 restrained tumor progression both in vivo and in vitro by the downregulation of c-Myc-mediated EMT pathway via CTCF-dependent positive feedback loop." (PMID 34775467, 2021).
tumor (continued). "In vivo studies of nude mice showed overexpression of circESRP1 effectively repressed xenograft tumor development and pulmonary metastasis, and inhibited c-Myc-mediated EMT progression by maintaining the low expression level of CTCF." (PMID 34775467, 2021). "Dysfunction of the TGF-β–regulated SPTBN1/SMAD3/CTCF complex increases stem cell–like properties in HCC cells and enhances tumorigenesis in tumor-initiating cells in a mouse model." (PMID 33457451, 2020). "Cell viability and migration assays showed that silencing CTCF, COL1A1, and COL1A3 inhibited the growth and migration of GC tumor cells." (PMID 33665169, 2020). "Therefore, CTCF may represent a new type of tumour suppressor gene." (PMID 30873749, 2019). "Thus the mechanism of CTCF inactivation could contribute to tumour subtype and prognosis." (PMID 28319062, 2017). "In tumour cell lines, where CTCF silences genes by DNA methylation, it has been shown that expression of BORIS can displace CTCF at these genes leading to local demethylation and gene activation." (PMID 24279897, 2013). "In the current study, we detected an association between expression of CTCF and histological grade where a high percentage of low-grade tumours that have a less proliferative activity showed positive nuclear expression, while the high-grade tumours mainly showed reduced or absent expression." (PMID 15354217, 2004). "Currently, there are limited reports on the tumor-related effects of RELA and CTCF." (PMID 41048344, 2025). "Two GRNs, albeit comprising a smaller number of tumor cells, showed high activity for the TCF7L2 regulon (along with KLF8, FOXK1, FOXP2, BACH1) (labeled TCF7L2+) and CTCF (along with MAFG and NR1H) (labeled CTCF+) respectively." (PMID 38645034, 2024). "Five transcription factors (CREB1, CTCF, YY1, E2F1, MYBL2) were significantly elevated with tumor progression in HCC, indicating that these potential transcription factors may be responsible for the upregulation of H3–H4 histone chaperones in HCC." (PMID 38561384, 2024). "Additionally, when comparing the findings from tumor samples that underwent testing using the expanded panel testing to the TCGA-UCEC cohort, a higher altered frequency of PIK3R1 and CTCF was identified in the TCGA cohort." (PMID 37730563, 2023). "CTCF, FOS, ATF2, and YY1 in H3F3B+ tumor cells were found to regulate angiogenesis." (PMID 37430270, 2023). "Within this CoRE in the tumour samples, we detected the formation of multiple H3K27ac peaks and a reduction in H3K9me3, but minor or no changes in CTCF and other histone marks." (PMID 36922594, 2023). "We further assessed the impact of CTCF expression in macrophages on supporting tumour metastasis in a PDAC mouse model of liver metastasis, in which PANC‐1 cells mixed with CTCF knockdown or control macrophages (THP‐1 shNC/sh1 CTCF cells) were injected into the spleens of BALB/c nude mice." (PMID 35184402, 2022). "As the CTCF gene is inactivated in metastatic tumors, its expression in MDA-MB-231 cells led to reduced cell migration in vitro after transfection with double plasmid CRISPR/Cas9-HDR system packed in tumor-targeted nanoparticles." (PMID 36139356, 2022). "In tumor cells, SEs at the MYC locus are looped to a common CTCF site within the MYC promoter." (PMID 35740532, 2022). "CRISPR/Cas9-mediated perturbation of a MYC promoter-proximal CTCF binding site in tumor cells leads to reduced chromatin interactions between the MYC promoter and distal SEs present downstream of MYC, indicating that the CTCF docking site is necessary in mediating enhancer–promoter looping." (PMID 35740532, 2022). "Hence, these data identified the role of circESRP1/miR-3942/CTCF axis and c-Myc-mediated EMT process for RCC tumor behavior." (PMID 34775467, 2021).
tumor (continued). "Dysfunction of TGF-β–regulated CTCF increases stem cell–like properties in HCC cells and enhances tumorigenesis in tumor-initiating cells in a mouse model, suggesting that defective TGF-β/CTCF might cooperate in liver tumor initiation." (PMID 33457451, 2020). "The LOX family has twice more partners in tumor cells than in normal cells, which induces a pathway switch from ECM organization to chaperone activity, a decrease in extracellular and secreted proteins and in the transcriptional repressor CTCF." (PMID 33383846, 2020). "Furthermore, we validated the expression of proteins and mRNAs related to CTCF and the ECM in tumor tissues and in aggressive and less aggressive GC cell lines." (PMID 33665169, 2020). "Thus, different tumor super-enhancers have the opportunity to form through diverse mechanisms throughout this large TAD and can exploit the MYC CTCF site to interact with and activate MYC expression." (PMID 29641996, 2018). "To date, modelling the full impact of CTCF haploinsufficiency on CTCF’s tumour suppressor function has not been previously examined." (PMID 30513694, 2018). "This provides the first evidence that CTCF inactivation in conjunction with inactivation of CDH1 and/or ZFHX3 and/or other candidate genes on 16q contributes to the development of poorer prognosis tumour subtypes." (PMID 28319062, 2017). "Additionally, in each tumor cell line we found a small number of regions occupied by BORIS alone (BORIS-only bound regions), but the same regions were occupied by CTCF in other cell lines." (PMID 26268681, 2015). "The data above support the multifunctional nature of CTCF, and at the same time show that CTCF is not essential for cell growth in culture or for tumor cells proliferation." (PMID 20119526, 2009). "Besides, the spleens of C57BL/6 mice were injected PANC02 cells and BMDM cells (BMDM siNC/siCTCF cells) which were interfered with CTCF and were not co‐cultured with tumour cells before injecting to examine the impact of CTCF." (PMID 35184402, 2022). "The newly transcribed LncRNA PACERR interacts directly with CTCF, forming the CTCF/PACERR complex to recruit HAT EP300, resulting in increased chromatin accessibility and transcriptional activation of PTGS2, the critical driver of M2 polarization and pro‐tumour functions in TAMs." (PMID 35184402, 2022). "Insulator binding protein CTCF (also known as 11-zinc finger protein or CCCTC-binding factor) is one of the key transcription factors that regulates the expression of ANRIL and these three tumor suppressor genes at the INK4/ARF locus by modulating the chromatin architecture." (PMID 30154386, 2018). "Additionally, the overlap of MCDRs with CTCF-bound loop anchors strongly suggested that MCR depletion was tied to 3D genome reorganization, whereby emerging or altered loops can bring distal regulatory elements into proximity to activate or repress key oncogenic or tumor-suppressive pathways." (PMID 40806343, 2025). "The different chromatin architecture and choice between DDR pathways might be a reason why the survival of mESC-AID-CTCF cells upon CTCF depletion does not meet our model predictions and also why the experimental data showed a different sensitivity between tumor and embryonic cells (respectively)." (PMID 35409255, 2022). "Because tumor super-enhancers can encompass genomic regions as large as 200 kb, and CTCF occupies sites that occur on average every 10 kb, there is considerable opportunity for super-enhancers to adventitiously contain a CTCF-bound site, which in turn could serve to interact with the MYC CTCF site." (PMID 29641996, 2018).
tumor (continued). "The levels of CTCF were elevated rather than decreased in pediatric ALL samples, which is not characteristic of a tumor suppressor and inspired us to further examine this finding." (PMID 24393203, 2014).